RN7SKP206 (RN7SK pseudogene 206)
Gene: Miscellaneous RNA gene on chromosome 8 (129,290,983 to 129,291,275, forward strand). Ensembl gene ENSG00000222755.
Homologues: Orthologues: mouse Gm54519 (56% identical). Paralogues in human: 7SK (73% identical), RN7SKP50 (73% identical), RN7SKP37 (73% identical), RN7SKP62 (72% identical), RN7SKP224 (72% identical), RN7SKP255 (72% identical), RN7SKP269 (72% identical), RN7SKP9 (72% identical), RN7SKP78 (72% identical), RN7SKP118 (71% identical), RN7SKP203 (71% identical), RN7SKP240 (71% identical), and 283 more.